LAYN (layilin)
Description:
Receptor for hyaluronate.
Synonyms: FLJ30977; FLJ31092
Tractability: Antibody: UniProt predicts a signal peptide or a membrane-spanning region. PROTAC: ubiquitination databases record sites on it.
Gene: Protein-coding gene on chromosome 11 (111,540,280 to 111,561,745, forward strand). Ensembl gene ENSG00000204381.
Subcellular location: Membrane
Subcellular location (Human Protein Atlas): Cytosol
Gene Ontology:
Molecular function: hyaluronic acid binding
Cellular component: focal adhesion; cell surface; ruffle; membrane
Genetic constraint (gnomAD): Loss-of-function variants: 26 observed, 33.35 expected, observed/expected ratio (o/e) 0.78, 90% interval 0.57 to 1.08. The upper end of that interval is the gene's LOEUF score, 1.08, which puts it in group 4 of 6, group 1 being the genes least tolerant of losing a copy. Missense variants: 418 observed, 416.74 expected, observed/expected ratio (o/e) 1, 90% interval 0.93 to 1.09. Synonymous variants: 153 observed, 160.19 expected, observed/expected ratio (o/e) 0.96, 90% interval 0.84 to 1.09.
Homologues: Orthologues: chimpanzee LAYN (99% identical), macaque LAYN (96% identical), dog LAYN (86% identical), guinea pig LAYN (86% identical), mouse Layn (84% identical), rabbit LAYN (84% identical), pig LAYN (79% identical), rat Layn (78% identical), tropical clawed frog layn (53% identical), zebrafish layna (48% identical), zebrafish laynb (35% identical). Paralogues in human: CHODL (36% identical).
Diseases named in the same sentence as LAYN in open-access papers:
LAYN is named in the same sentence as 71 diseases in open-access papers, as found by Europe PMC text mining. Sharing a sentence is not in itself a finding about the gene and the disease. The quoted sentences say what the papers report.
breast carcinoma (10 papers, 2019 to 2025). "In our study, the genetic elevation of LAYN protein levels is associated with increased breast cancer risk, suggesting a LAYN inhibitor would be desired for the treatment of breast cancer." (PMID 37996402, 2023). "In contrast, lower expression of LAYN was observed in bladder urothelial cancer, breast cancer, colorectal cancer, kidney chromophobe, lung adenocarcinoma, prostate cancer, thyroid cancer, and endometrial cancer compared with adjacent normal tissues." (PMID 38430385, 2024). "Of those, we present five proteins (CD160, DNPH1, LAYN, LRRC37A2 and TLR1) that show a potential causal role in breast cancer risk with confirmatory results in independent cohorts." (PMID 37996402, 2023). "In conclusion, by applying an MR approach to a broad range of circulating proteins we found that genetically elevated CD160, DNPH1, LAYN, LRRC37A2 and TLR1 were associated with breast cancer." (PMID 37996402, 2023). "To summarise, the MR analysis showed that genetic elevation of CD160, DNPH1, LAYN, LRRC37A2 and TLR1 associated with breast cancer risk, and with similar effects on ER+ and ER− cancers." (PMID 37996402, 2023). "We found that genetically lower levels of CD160 and LRRC37A2 and genetically higher levels of DNPH1, LAYN and TLR1 were associated with increased risk of breast cancer." (PMID 37996402, 2023). "Taken together, these data indicate that the adhesion of the breast cancer cell line MDA-MB-231 to bmMSC is mediated by the HA receptor layilin and in turn results in reduced motility of cancer cells in the presence of undifferentiated bmMSCs." (PMID 34707175, 2021). "Moving on, LAYN was mainly considered an adverse prognostic factor in brain cancer (glioma), colorectal, and ovarian cancer, while it indicated a positive prognostic role in breast cancer." (PMID 39064019, 2024). "However, mechanistic studies will be required to confirm the direction of effect proposed by the MR evidence and to validate LAYN as a drug target in breast cancer." (PMID 37996402, 2023). "In addition, we show that metastatic breast cancer cell lines actively seek close proximity to MSCs in dependence of their HA-receptor layilin, positively modulate the MSC HA-system and prevent MSC’s lineage commitment towards adipogenic differentiation." (PMID 34707175, 2021). "However, LAYN expression has less influence on breast cancer, and shows a better OS in lung cancer." (PMID 30761122, 2019). "Lead pQTL in cis-regions for CD160, LAYN and TLR1 were not the variants with the lowest p-values for breast cancer risk but were localised in the same, size-limited, genomic region." (PMID 37996402, 2023).
lung carcinoma (8 papers, 2011 to 2025). "MALAT-1, a long non-coding RNA (lncRNA), mediates LAYN upregulation, enhancing tumor cell motility and implicating layilin as a driver of lung cancer aggressiveness." (PMID 41404063, 2025). "These T cells appeared to resemble a recently described IL7R-HAVCR2+KRT86+DUSP4+LAYN+ subset, which has been associated with response to anti-PD1 therapy in lung cancer." (PMID 39312285, 2024). "Studies showed that layilin is related to lymphatic metastasis, adhesion, migration, and invasion in lung cancer." (PMID 35770160, 2022). "Low level of LAYN protein reduced cell invasion and lymph node metastasis in A549 lung cancer cells, which was the first proof that LAYN was related to cancer." (PMID 36260222, 2022). "LAYN was first shown to be associated with cancer in a report demonstrating that low levels of LAYN protein can reduce cell invasion and lymph node metastasis A549 lung cancer cells." (PMID 30761122, 2019). "Recently layilin has been suggested to play a crucial role in lymphatic metastasis of lung carcinoma A549 cells." (PMID 21740549, 2011). "Previously, it was indicated that LAYN, CCT4, CTHRC1, and FHL1 gene were correlated with the migrational potential of lung cancer cells." (PMID 27586393, 2016).
gastric cancer (7 papers, 2019 to 2024). A primary or metastatic malignant neoplasm involving the stomach. "Previous studies have shown that LAYN regulated the immune balance among tumor-associated macrophages (TAMs), dendritic cells, and regulatory T cells (Tregs) in colon and gastric cancer tissues, and affected tumor cell progression." (PMID 38430385, 2024). "The findings in this report shed light on the important role of LAYN in colorectal and gastric cancers as well as provide a potential relationship and an underlying mechanism between LAYN and tumor-immune interactions." (PMID 30761122, 2019). "To better understand the relevance and underlying mechanisms of LAYN expression in cancer, we investigated the relationship between the LAYN expression and clinical characteristics of gastric cancer patients in the Kaplan-Meier plotter databases." (PMID 30761122, 2019). "In addition, LAYN expression potentially contributes to regulation of tumor-associated macrophages (TAMs), DCs, T cell exhaustion and Tregs in colon and gastric cancer." (PMID 30761122, 2019). "Previous studies have shown that LAYN was correlated with poor prognosis and tumor immune cell infiltration in colorectal cancer, gastric cancer, and hepatocellular carcinoma." (PMID 38430385, 2024). "The high expression of LAYN was significantly associated with poor overall survival (OS) and progression-free survival (PFS) in gastric cancer patients." (PMID 35912206, 2022). "Correlation of LAYN mRNA expression and clinical prognosis in gastric cancer with different clinicopathological factors by Kaplan-Meier plotter." (PMID 30761122, 2019). "Interestingly, increased levels of LAYN expression can impact the prognosis of patients who have gastric cancer with lymph node metastasis indicating that LAYN expression can be used as a predictor of tumor metastasis." (PMID 30761122, 2019). "In addition, LAYN expression may contribute to the regulation of TAMs, DCs, T-cells, and Tregs in colon and gastric cancers." (PMID 37901223, 2023). "LAYN is a key gene in the regulation of immunity, and a bioinformatics analysis showed that LAYN is associated with prognosis and the level of immune infiltration of CD8+ T cells, CD4+ T cells, macrophages, neutrophils, and DCs in patients with several cancers, especially colon and gastric cancers." (PMID 37901223, 2023). "For example, Pan and colleagues found that layilin (LAYN) is a new prognostic and immune infiltration marker in gastric cancer." (PMID 34425560, 2021). "In summary, increased LAYN expression correlates with poor prognosis and increased immune infiltration levels in CD8+ T cells, CD4+ T cells, macrophages, neutrophils and DCs of multiple cancers, especially in colon and gastric cancers." (PMID 30761122, 2019). "In addition, high LAYN expression was significantly correlated with poor OS and progression-free survival (PFS) in gastric cancers (OS HR = 1.97, P = 3.6e-10; PFS HR = 2.12, P = 2.3e-10)." (PMID 30761122, 2019). "In addition, high level of LAYN expression was shown to be correlated with poor prognosis of gastric cancer in stage 2 to 4, T2 to T4 and N1 to N3, with the highest HR for poor OS and PFS when LAYN was highly expressed in gastric cancer." (PMID 30761122, 2019). "Specifically, high LAYN expression was correlated with worse OS and PFS in stage 2 to 4 but not stage 1 and stage N0 gastric cancer patients (P = 0.28, 0.34; P = 0.073, 0.092)." (PMID 30761122, 2019).
colorectal cancer (6 papers, 2019 to 2024). A primary or metastatic malignant neoplasm that affects the colon or rectum. "Actually, a dendritic cell-infiltrating level has been reported to be positively correlated with layilin and a high layilin level was linked to poor survival in colorectal cancer patients." (PMID 35480120, 2022). "There are several studies which have identified single gene like PDL-1, Layilin and Apolipoprotein E with prognostic significance in colorectal cancer." (PMID 31387239, 2019). "LAYN expression is a specific signature present in colorectal cancer (CRC) and non-small cell lung changer (NSCLC) infiltrating regulatory T lymphocytes (Treg) from CRC and NSCLC patient samples." (PMID 30761122, 2019). "In addition, LAYN was identified as a Treg cell signature gene, and its high expression was correlated with poor prognosis in patients with non-small-cell lung cancer and colorectal cancer." (PMID 38430385, 2024).
colon cancer (5 papers, 2019 to 2023). "As elucidated in other research, LAYN was identified as a prognostic biomarker and is highly correlated with immune infiltrates in gastric and colon cancers." (PMID 33490290, 2020). "Another important aspect of this study is that LAYN expression is correlated with diverse immune infiltration levels in cancer, especially in gastric and colon cancers." (PMID 30761122, 2019). "Most ICGs showed low mutation levels in colon cancer cases, except CD2, VTCN1, and LAYN." (PMID 34912802, 2021). "In addition, in gastic and colon cancers, LAYN expression potentially contributes to the regulation of tumor-associated macrophages (TAMs), DCs, T cell exhaustion, and Tregs." (PMID 30761122, 2019). "Therefore, LAYN likely plays an important role in immune cell infiltration and as a prognosis biomarker in patients with gastric and colon cancers." (PMID 30761122, 2019).
hepatocellular carcinoma (4 papers, 2020 to 2024). A malignant tumor that arises from hepatocytes. "LAYN, encoding layilin, was recently reported to be highly expressed in Tregs isolated from hepatocellular carcinoma." (PMID 36466840, 2022). "Meanwhile, clonal enrichment of infiltrating exhausted CD8+ T cells and Tregs with high expression of layilin (LAYN) was found in hepatocellular carcinoma." (PMID 36154923, 2022). "Tumor-infiltrating lymphocytes are a potential benefit of immunotherapy and enhance clinical response to cancer, and analysis of the T-cell population in hepatoma tissues revealed that the LAYN gene in infiltrating T cells can inhibit the function of regulatory T cells and CD8 T cells." (PMID 33142921, 2020). "The analysis indicated that LAYN expression was higher in HNSCC, hepatocellular carcinoma, cholangiocarcinoma, and renal clear cell carcinoma than in their respective adjacent normal tissues." (PMID 38430385, 2024).
liver cancer (4 papers, 2022). An epithelial or non-epithelial malignant neoplasm that arises from the liver. "Overall, the survival analysis based on the DEGs suggests that the expression of POSTN, HTRA3, LAYN, AFM and AANAT are associated with the outcomes of patients with liver cancer." (PMID 35676936, 2022). "This suggests that LAYN is fully involved in the immune infiltration of liver cancer and plays an important role in the development of tumor." (PMID 35676936, 2022). "LAYN, which is associated with the suppressive function of exhausted CD8 T cells in NSCLC24 and liver cancer, however, exhibited a sporadic expression in SCLC." (PMID 36195615, 2022). "For example, LAYN, linked to the suppressive function of tumor Treg and exhausted CD8+ T cells, was recently reported to be highly expressed in Tregs isolated from lung, colon and liver cancers." (PMID 35664061, 2022). "Moreover, TMAO upregulates POSTN, NAPB, LAYN, and HTRA3 in liver cancer, and high expression levels of these genes are closely associated with suppression of the immune microenvironment and patient survival outcomes in liver cancer." (PMID 35676936, 2022). "Upregulation of POSTN, LAYN and HTRA3 and downregulation of AANAT and AFM were positively related to poorer overall survival in human liver cancer." (PMID 35676936, 2022). "Interestingly, higher expression of POSTN (OS HR = 1.63, 95% CI = 1.13–2.33, p = 0.0076; DSS HR = 1.8, 95% CI = 1.11–2.93, p = 0.016), LAYN (DSS HR = 1.61, 95% CI = 1.02–2.55, p = 0.039) and HTRA3 (OS HR = 1.53, 95% CI = 1.08–2.17, p = 0.015) were associated with poorer outcomes in liver cancer." (PMID 35676936, 2022). "By analyzing the DEGs of the two types of cells, they found that the gene Layilin can inhibit the killing function of CD8+ T cells and may become a potential target for liver cancer immunotherapy." (PMID 35799608, 2022).
lung adenocarcinoma (4 papers, 2019 to 2025). A carcinoma that arises from the lung and is characterized by the presence of malignant glandular epithelial cells. "Elevated expression of layilin predicts a better response to anti-VEGFR2 and anti-PD-1 combination therapy in lung adenocarcinoma, which is mechanistically linked to the downregulation of layilin in tumor-infiltrating CD8+ T cells." (PMID 41404063, 2025). "Genetic suppression of layilin reduces metastatic progression and extends survival in murine models of lung adenocarcinoma." (PMID 41404063, 2025).
melanoma (3 papers, 2022 to 2025). A malignant, usually aggressive tumor composed of atypical, neoplastic melanocytes. "In human melanoma, LAYN is one of the most enriched genes among the phenotypically exhausted yet clonally expanded tumour-infiltrating lymphocytes." (PMID 39202425, 2024). "We designed experiments by overexpressing LAYN on CD8+T cells in LUAD, but Mahuron KM designed experiments by knocking out LAYN on CD8+T cells in melanoma." (PMID 36260222, 2022). "Interestingly, high LAYN and HAVCR2 expression levels were found to be associated with anti-PD1 therapy when administered in melanoma and NSCLC-HNSC-melanoma in other studies, respectively." (PMID 40076932, 2025).
allergic disease (2 papers, 2024 to 2025). An immune response that occurs following re-exposure to an innocuous antigen, and that requires the presence of existing antibodies against that antigen. "Our study demonstrates a causal association between the expression levels of TNFAIP3 and LAYN and the risk of allergic diseases, suggesting them as potential drug targets for these conditions, warranting further clinical investigation." (PMID 38573314, 2024). "The elevation of TNFAIP3 protein levels is associated with a reduced risk of allergic diseases, whereas the increase in LAYN protein levels is correlated with an elevated risk of allergic diseases." (PMID 38573314, 2024). "An increase in TNFAIP3 protein levels was negatively correlated with the risk of allergic diseases, whereas an increase in LAYN protein levels was positively correlated with the risk of allergic diseases." (PMID 38573314, 2024). "Bayesian co‐location analysis showed that TNFAIP3 and LAYN may have the same variants as allergic diseases." (PMID 38573314, 2024). "Asthma is an allergic disease, and we found that IL1R1 and Layilin are both associated with allergic diseases, whereas ECM1 is related to atopic dermatitis." (PMID 39806440, 2025). "Through MR and Bayesian colocalization analysis, we identified TNFAIP3 and LAYN as potential drug targets for allergic diseases." (PMID 38573314, 2024). "Bayesian colocalization analysis suggested that LAYN (coloc.abf‐PPH4 = 0.819) and TNFAIP3 (coloc.abf‐PPH4 = 0.930) share the same variant associated with allergic diseases." (PMID 38573314, 2024). "In summary, we have identified four small molecular compounds that can upregulate TNFAIP3 expression and four that can downregulate LAYN expression, providing insights for targeted therapy of allergic diseases." (PMID 38573314, 2024). "Following sensitivity analysis and MR analysis, we identified two proteins among the 11 significant ones as potential drug targets for allergic diseases, namely LAYN and TNFAIP3." (PMID 38573314, 2024). "Next, we performed Bayesian co‐localization analysis, and the results suggested that LAYN (coloc.abf‐PPH4 = 0.819) and TNFAIP3 (coloc.abf‐PPH4 = 0.930) share the same variant with allergic diseases." (PMID 38573314, 2024). "In this study, we identified LAYN as a potential drug target for allergic diseases through MR and Bayesian co‐location analysis." (PMID 38573314, 2024). "This study suggests that TNFAIP3 and LAYN may serve as potential drug targets for allergic diseases." (PMID 38573314, 2024). "Our research shows that TNFAIP3 and LAYN are potential drug targets for allergic diseases." (PMID 38573314, 2024). "The identified proteins may serve as attractive drug targets/biomarker for allergic diseases, particularly TNFAIP3 and LAYN." (PMID 38573314, 2024).
asthma (2 papers, 2024 to 2025). "Conversely, an increase in ADAM19 (OR = 0.87; 95% CI 0.82–0.92; P = 6.17 × 10−7) and Layilin (OR = 0.61; 95% CI 0.51–0.73; P = 1.14 × 10−7) decreased the risk of asthma." (PMID 39806440, 2025). "Colocalization analysis indicated that ECM1 (coloc.abf-PPH4 = 0.953), IL-6 sRa (coloc.abf-PPH4 = 0.966), and layilin (coloc.abf-PPH4 = 0.975) shared the same genetic variation as in asthma." (PMID 39806440, 2025). "Through colocalization analysis of the seven initially identified proteins, three proteins were identified as potential drug targets for asthma, including ECM1, IL-6 sRa, and layilin." (PMID 39806440, 2025). "Our study demonstrated a causal relationship between genetic determinants, including IL1R1, IL7R, ECM1, CD200R1, ADAM19, IL-6 sRa, and Layilin (LAYN) protein levels, and asthma." (PMID 39806440, 2025). "Moreover, the identified proteins may serve as attractive drug targets for asthma, especially ECM1 and Layilin (LAYN)." (PMID 39806440, 2025). "Additionally, the identified proteins may serve as attractive drug targets for asthma, particularly ECM1 and Layilin (LAYN)." (PMID 39806440, 2025). "As LAYN and IGFLR1 appear to play a role in the immune response of asthmatic patient-derived ILC2s, these genes could also have the potential to be valuable targets for the treatment of asthma." (PMID 39052598, 2024).
cholangiocarcinoma (2 papers, 2019 to 2024). A carcinoma that arises from the intrahepatic biliary tree (intrahepatic cholangiocarcinoma) or from the junction, or adjacent to the junction, of the right and left hepatic ducts (hilar cholangiocarcinoma). "However, LAYN expression was significantly higher in CHOL (cholangiocarcinoma), HNSC (head and neck cancer), KIRC (kidney renal clear cell carcinoma), and LIHC (liver hepatocellular carcinoma) compared with adjacent normal tissues." (PMID 30761122, 2019).